CRP (C-reactive protein)
Diseases named in the same sentence as CRP in open-access papers (continued):
Sharing a sentence is not in itself a finding about the gene and the disease.
scrub typhus (31 papers, 2012 to 2026). Scrub typhus is a rare dust mite-borne infectious disease caused by the Orientia tsutsugamushi bacterium and characterized clinically by an eruptive fever which is potentially serious. "A retrospective case-control study in Korea, demonstrated that CRP levels associated with poor prognosis in patients with scrub typhus." (PMID 35925895, 2022). "Female sex and hepatomegaly were associated with scrub typhus, and an age of 15 years or younger, vomiting, cough, and a C-reactive protein (CRP) concentration of more than 5 mg/L were associated with leptospirosis." (PMID 24748368, 2013). "Laboratory investigations demonstrated elevated C-reactive protein (CRP) levels and confirmed the diagnosis of scrub typhus through a positive IgM antibody by enzyme-linked immunosorbent assay (ELISA)." (PMID 41328087, 2025). "Most scrub typhus and murine typhus patients had elevated liver aminotransferases, creatinine, procalcitonin, C-reactive protein, and bilirubin." (PMID 30882318, 2019). "That is, elevated serum TNF-α, CRP level, and modified APACHE II score were associated with poor prognosis in patients with scrub typhus." (PMID 30909868, 2019). "ABI and CRP were simultaneously associated with an elevated leukocyte count and ARF in patients with scrub typhus." (PMID 31581612, 2019). "A broad estimate for the cost per DALY averted for the three tests suggests that either the scrub typhus or CRP testing is likely to be cost-effective even at low WTP thresholds, despite the considerable uncertainty surrounding many model parameters." (PMID 27027303, 2016). "As a result of inflammation or infection of scrub typhus, 90.9% of patients had elevated C-reactive protein levels and 45.0% had an elevated erythrocyte sedimentation rate (ESR)." (PMID 25954814, 2015). "All testing strategies are likely to result in higher average costs, but only the scrub typhus and CRP tests are likely to be cost-effective when considering direct health benefits, with median cost per disability adjusted life year averted of approximately $48 USD and $94 USD, respectively." (PMID 27027303, 2016). "Both typhus forms demonstrated similar disease severities and complication rates, but the levels of albumin (reduced, but within the normal range) and CRP (elevated) in patients with scrub typhus suggest that inflammation might play a more important role in scrub typhus than in murine typhus." (PMID 22192733, 2012). "Our study found that both serum CRP and PCT values rose in the acute phase and declined in the convalescent phase in acute Q fever, scrub typhus, and murine typhus." (PMID 32398008, 2020). "Markers (TNF-α level, CRP level, WBC count, and modified APACHE II score) were compared across deceased patients and those with severe and mild scrub typhus." (PMID 30909868, 2019). "Thus, although plasma levels of CRP, PTX-3 and IL-6 were markedly raised in scrub typhus patients, similar levels were found in infectious disease controls." (PMID 24516677, 2014).
upper respiratory tract infection (31 papers, 2011 to 2026). "During acute upper respiratory tract infections (AURTIs) caused by Adenoviruses, the mix of severe clinical presentation, together with elevation of white blood cells (WBCs) and C-reactive protein (CRP), often mimicking bacterial infection, leads to an inappropriate use of antibiotics." (PMID 33066100, 2020). "Among eight selected parameters, GLU and ALB are usually influenced by the short/long-term dietary pattern, and CRP is often increased by stochastic factors such as upper respiratory tract infections." (PMID 39882130, 2024). "The positive association between CRP level and antibiotic prescribing is in line with previous results from Denmark, where 75% of patients with an upper respiratory tract infection were prescribed antibiotics if their CRP was > 50 mg/l." (PMID 38184547, 2024). "One subject had infection of the upper respiratory tract and one affected hypersensitive C-reactive protein elevation." (PMID 37828535, 2023). "Several studies have shown that CRP levels are higher in bacterial than viral upper respiratory tract infections." (PMID 37328771, 2023). "POC CRP testing has previously been shown to reduce antibiotic prescribing in upper respiratory tract infections." (PMID 25277543, 2014). "Throughout the course, we observed that persistent fever and elevated CRP often resolved, contrary to expectations, when the patient had symptoms of an upper respiratory tract infection." (PMID 22924145, 2012). "The raised CRP could be attributed to his upper respiratory tract infection that he acquired 5 days prior to the presentation of his vasculitic rash." (PMID 40666239, 2025). "Clinical analysis showed that neurologic complications were significantly higher in EV71-infected patients, while the proportion of upper respiratory tract infections (URTIs) and the levels of C-reactive protein (CRP) were significantly higher in CVA16-infected patients." (PMID 24776922, 2014). "Thirdly, the change of the target of immune response from ever-present chimeric cells to foreign pathogen might be accountable for the resolution of fever and elevated CRP level during infectious diseases such as upper respiratory tract infections." (PMID 22924145, 2012). "The use and advantages of point-of-care tests (POCTs) for C-reactive protein (CRP) in general practice, especially for upper respiratory tract infections (uRTIs), have been studied extensively." (PMID 39313318, 2025). "We present a case series of four HAE patients who had C4, C1-INH, c-reactive protein (CRP) and ferritin measured at baseline and again during a self-reported upper respiratory tract infection (URTI) or flu-like illness." (PMID 34627363, 2021). "Secondary outcomes were changes in plasma C-reactive protein (CRP), the diversity of the faecal microbiota, quality of life (QoL) assessments and the incidence of upper respiratory tract infection (URTI)." (PMID 32144319, 2020). "The laboratory investigations showed that CRP levels increased with a normal or slightly elevated leucocyte count, and common upper respiratory tract infection was ruled out in all of the patients with negative sputum smear results and respiratory virus screening." (PMID 39118282, 2024). "We found that antibiotics were still widely used for self-limiting upper respiratory tract infections (26.0% in the control group and 23.1% in the intervention group), despite the majority of tested patients having a low CRP concentration and consequently not requiring antibacterial treatment." (PMID 36127630, 2022). "Febrile controls exhibited significantly higher CRP levels (CRP 11.5 mg/l, IQR 8.25–45.75 mg/l) compared to children with FS (CRP 5 mg/l, IQR 0–7 mg/l; p = 0.016) at presentation and were more frequently diagnosed with lower than upper respiratory tract infections." (PMID 30605489, 2019).
age-related macular degeneration (30 papers, 2007 to 2025). Age-related loss of vision in the central portion of the retina (macula), secondary to retinal degeneration. "Previous research utilizing MR analysis has successfully demonstrated causal relationships between FT4 and TSH levels with C-reactive protein, age-related macular degeneration (AMD), and atrial fibrillation." (PMID 38090267, 2023). "Higher levels of the systemic inflammatory markers CRP and IL-6 are independently associated with progression of age-related macular degeneration (AMD)." (PMID 17374166, 2007). "The role of CRP has been implicated in the pathogenesis of age-related macular degeneration (AMD) by immunohistochemical evidence that showed clear changes in distribution and relative levels of CRP and complement factor H (CFH) in early and late AMD eyes." (PMID 23516433, 2013). "Some studies previously demonstrated that the ratio of monomeric to pentameric forms of CRP was substantially elevated in some inflammatory autoimmune diseases, particularly adult-onset Still’s disease and age-related macular degeneration." (PMID 39867895, 2024). "MR analysis has been used to investigate the impact of education levels, vitamin D, or medication on myopia; and lipid levels, refractive errors, or c-reactive protein levels on age-related macular degeneration." (PMID 36980914, 2023). "Choroidal neovascularization (CNV) and inflammation play an important role in retinal disease development and the acute phase reactant C-reactive protein (CRP) has been shown to contribute to Age-related macular degeneration (AMD) in vitro." (PMID 40858941, 2025). "HDL, high-density lipoprotein cholesterol; LDL, low-density lipoprotein cholesterol; CRP, C-reactive protein; AMD, age-related macular degeneration; ANCOVA, analysis of covariance." (PMID 38333436, 2024). "The results of degenerative macular diseases were different from the MR study of CRP on age-related macular degeneration (AMD) that highlighted higher circulating CRP levels leading to increases in risk for all forms of AMD." (PMID 34386016, 2021). "“n”, sample size; %, percentage; HDL, high-density lipoprotein cholesterol; LDL, low-density lipoprotein cholesterol; CRP, C-reactive protein; AMD, age-related macular degeneration." (PMID 38333436, 2024). "Researchers have proposed a possible correlation between age-related macular degeneration (AMD) and inflammation or C-reactive protein (CRP) levels." (PMID 38672162, 2024). "A relatively recent meta-analysis showed that Age-Related Macular Degeneration (ARMD) is not as associated with CRP at early ages compared to older ages as it can show small-to-moderate increases (>3 mg/L), and also, CRP can show relatively similar values for choroidal thinning during ARMD." (PMID 37873776, 2023). "Both CRP and PTX3 are expressed and upregulated under inflammatory conditions and may deposit locally at the site of tissue damage, also in complement-related diseases such as age-related macular degeneration and atypical hemolytic uremic syndrome." (PMID 32765490, 2020).
cervical cancer (30 papers, 2015 to 2026). A primary or metastatic malignant neoplasm involving the cervix. "Albumin-CRP ratio is a known biomarker for cervical cancer progression, which supports the association between ICC and PhenoAA in our study." (PMID 35570901, 2022). "Nevertheless, several biomarkers such as CRP and albumin were found to be associated with shorter survival in patients with cervical cancer, suggesting inflammatory reactions of the body to affect the individual’s oncological outcome." (PMID 30737542, 2019). "Serum albumin levels, CRP, neutrophils, and platelet counts, for instance, seem to be associated with tumor stage and survival in patients with cervical cancer." (PMID 30737542, 2019). "Veritably, elevated CRP, one of the major acute-phase proteins synthesized by the liver, was found to be associated with advanced disease and shorter survival in various malignancies, including cervical cancer." (PMID 30535923, 2019). "Some studies have also shown that the C-reactive protein /ALB ratio was closely related to the prognosis of cervical cancer." (PMID 37875880, 2023). "It would be more useful if models for predicting clinical outcomes in cervical cancer were developed not only with CBC profiles but also with other potential biomarkers such as CRP." (PMID 32933192, 2020). "Reports of CRP level in relationship to blood albumin level (i.e. the CRP/albumin ratio) as a novel prognostic index for survival for cervical cancer have appeared." (PMID 33324413, 2020). "Furthermore, a meta-analysis including 2204 patients with cervical cancer determined a higher CRP as a significant predictor of poor PFS and OS." (PMID 39851955, 2025). "A study comprising 91 cervical cancer cases discovered a correlation between low hemoglobin and elevated levels of reactive oxygen species, CRP, IL-1, TNF-α, ß, and IL-6, multivariate analysis revealed that IL-6 was a separate factor influencing hemoglobin levels." (PMID 41142623, 2025). "Similarly, the present study revealed a shorter PFS and OS in cervical cancer patients with elevated CRP values." (PMID 39851955, 2025). "Furthermore, elevated plasma CRP levels correlate with reduced progression-free and overall survival across various solid tumors, including glioblastoma multiforme, cervical cancer, anal cancer, and NSCLC, as confirmed by multivariate analyses." (PMID 40420174, 2025). "The CRP and PIV may help better risk stratification for prognosis prediction of patients with cervical cancer." (PMID 39851955, 2025). "On the other hand, we tested the CRP/Alb ratio in predicting the outcome of VC because this novel marker has gained significant attention recently for its ability to detect malnutrition and systemic inflammation in ovarian and cervical cancers." (PMID 36614896, 2022). "The role of inflammatory biomarkers such as NLR, PLR, MLR, CRP, and PIV have been studied in the prognosis of cervical cancer." (PMID 39851955, 2025). "The inclusion of inflammatory markers such as NC, CRP, and NLR in our predictive model was consistent with recent research that highlights their prognostic significance in cervical cancer." (PMID 40386558, 2025). "Regarding immunotherapy with aniti-PD-1/PD-L1 antibody, pretreatment serum CRP concentrations emerged as independent predictors of both PFS and OS rates in R/M cervical cancer patients undergoing immunotherapeutic interventions." (PMID 41409282, 2025). "We aimed to investigate the effect of glucose/c-reactive protein (CRP) ratio [GCR], which shows these two parameters together, on PFS in cervical cancer." (PMID 38783223, 2024). "Although there have been previous studies with glucose and CRP, for the first time we demonstrated the prognostic importance of GCR for PFS in cervical cancer and our comparison with the healthy control group was more significant." (PMID 38783223, 2024).
cervical cancer (continued). "Coupled with the evidence above, previously reported associations between PhenoAge components, including serum glucose, albumin, and C-reactive protein (CRP), and cervical cancer also support the biological plausibility of our study." (PMID 35570901, 2022). "Additionally, numerous studies have demonstrated a strong correlation between inflammatory markers, such as neutrophil count (NC), C-reactive protein (CRP), and the neutrophil-to-lymphocyte ratio (NLR), and the prognosis of cervical cancer." (PMID 40386558, 2025). "The correlation between glucose and CRP, both metabolic and inflammation indicators, and cervical cancer prognosis has not been reported in the literature." (PMID 38783223, 2024). "Hence, we decided to combine CRP and serum albumin to create a new inflammatory prognostic factor in stage IB‐IIA cervical cancer." (PMID 29193777, 2018). "Accordingly, inflammation-based prognostic indicators, such as the modified Glasgow Prognostic Score (mGPS), platelet to lymphocyte ratio (PLR), neutrophil to lymphocyte ratio (NLR), albumin, and C-reactive protein (CRP) are prognostic factors for cervical cancer as well as other cancers." (PMID 26885692, 2016). "In addition, levels of C-reactive protein (CRP) and albumin (ALB), among circulating inflammatory proteins closely related to systemic nutritional status, are valuable prognostic indicators for many malignancies, including cervical cancer." (PMID 37729271, 2023).
urticaria (30 papers, 2013 to 2026). A vascular reaction of the skin characterized by erythema and wheal formation due to localized increase of vascular permeability. "Studies have revealed associations between severity of urticaria and serum biomarkers, including D-dimer, C-reactive protein (CRP), total IgE, IL-6, and vascular endothelia growth factor (VEGF) though the validity of these biomarkers remains controversial." (PMID 27057079, 2016). "Therefore, it is feasible that C-reactive protein, a widely used inflammatory response marker, is associated with Chronic Spontaneous Urticaria activity similar to blood clotting markers." (PMID 33640190, 2021). "An elevated CRP, in addition to suggesting an infection, correlates with urticaria activity and quality-of-life impairment, as well as inflammatory and coagulation markers, and CRP is significantly higher in patients unresponsive to H1-antihistamines." (PMID 40546743, 2025). "Our patient exhibited elevated inflammatory markers (CRP and SAA), urticaria-like rash, sensorineural hearing loss, and chronic aseptic meningitis, meeting the diagnostic criteria for early diagnosis." (PMID 40852416, 2025). "CRP can also be observed in other conditions, such as urticaria exacerbations or other cutaneous manifestations, where it has proven to have a significant association." (PMID 37763241, 2023). "IL-6 is an acute phase protein closely related to the production of CRP and fibrinogen, whose levels are elevated during urticaria exacerbations." (PMID 36539847, 2022). "If the urticaria progresses and becomes chronic spontaneous urticaria it is worthwhile, at this time, performing a full blood count and differential and either CRP, ESR, so that these can be included in the referral letter." (PMID 36225262, 2022). "The exception should be made in cases of cold-induced urticaria, in which complete blood count and sedimentation rate/C-reactive protein should be performed." (PMID 35949781, 2022). "CINCA/NOMID patients present with congenital, usually persistent, urticaria-like rash accompanied by neutrophilic leucocytosis and high level of CRP and showing typical facies characterized by frontal bossing, saddle-back nose and large cephalic perimeter." (PMID 36275641, 2022). "Contrary to previous work, we confirmed a positive correlation between IL-17A levels and CRP in all patients with urticaria." (PMID 36539847, 2022). "These include raised inflammatory markers (CRP/SAA) plus at least two of six CAPS-typical symptoms (urticaria-like rash, cold-triggered episodes, sensorineural hearing loss, musculoskeletal symptoms, chronic aseptic meningitis and skeletal abnormalities)." (PMID 30175395, 2018). "Patient P1 presented at age 11 days with high-grade fever, urticaria-like rash, and increased acute-phase reactant C-reactive protein levels." (PMID 29778503, 2018). "Our previous findings showed the importance of analysing the peripheral markers of acute phase response (APR) activation, C-reactive protein (CRP) and IL-6 in the context of urticaria activity and severity." (PMID 23207551, 2013). "In our study, despite low levels, in children with single episode of urticaria IL-1β correlated with CRP and D-dimer levels (marker of coagulation pathway activation)." (PMID 24490166, 2013). "In children with single episode of urticaria serum concentration of IL-1RA correlated with CRP, D-dimer, and IL-1β levels (r = 0.379, P = 0.019; r = 0.66, P = 0.001; and r = 0.34, P < 0.05, resp)." (PMID 24490166, 2013). "In children with single episode of urticaria, level of IL-1RA correlated with C-reactive protein (CRP), D-dimer, and IL-1β levels." (PMID 24490166, 2013). "In contrast, high disease activity, inducible urticaria, elevated CRP or IL-6 levels, and hematological features such as increased neutrophil-to-lymphocyte ratio, basopenia, eosinopenia, and markers of coagulation activation (e.g., D-dimer, fibrinogen) are linked to resistance." (PMID 41602870, 2026).